TYROBP (transmembrane immune signaling adaptor TYROBP)
Diseases named in the same sentence as TYROBP in open-access papers (continued):
Sharing a sentence is not in itself a finding about the gene and the disease.
breast carcinoma (19 papers, 2017 to 2024). "Previous study has uncovered an association between high TYROBP expression with high-risk metastases as well as poor survival of breast cancer patients." (PMID 38817876, 2024). "In breast cancer, higher levels of TYROBP expression have been associated with worse clinical outcomes, including shorter overall survival and disease-free survival." (PMID 37207157, 2023). "For example, TYROBP expression has been found to be increased in several types of cancer, including breast cancer, lung cancer, and low-grade glioma." (PMID 37207157, 2023). "Previous investigations have indicated that TYROBP is overexpressed and related to tumor progression in several cancers such as glioblastoma, gastric cancer, osteosarcoma, and breast cancer." (PMID 35265561, 2022). "Studies show that high TYROBP expression in breast cancer cells is correlated with bone metastasis and poor prognosis." (PMID 34162355, 2021). "Among the candidate CpGDMs, we found eight genes with differential methylation previously associated with breast cancer susceptibility and pathology in the G2SBC and COSMIC Databases (AMOTL1, CDCP1, CYFIP1, MAP3K6, MIB2, SDK1, TAL1, and TYROBP)." (PMID 33145876, 2021). "It has been found that TYROBP is up‐expressed in breast cancer cells and is significantly related to skeletal metastasis and poor prognosis." (PMID 33015999, 2020). "TYROBP, also known as KARAP/DAP12 (killer cell activating receptor‐associated protein/DNAX activating protein of 12 kDa), has been found to be linked with the poor prognosis and skeletal metastasis of breast cancer." (PMID 34926275, 2021). "In addition, a significant difference was observed between the mean intensity of TYROBP in patients’ PBMCs and breast cancer cell lines [SKBR3 (p = 0.022), MCF7 (p = 0.007)]." (PMID 31370904, 2019). "However, the authors found that 75% of breast cancer patients with CTCs were TYROBP positive." (PMID 36595751, 2022). "TYROBP/ITAM pathway may be involved in bone metastasis of breast cancer." (PMID 33015999, 2020). "Quantification of TYROBP expression in breast cancer cell lines and in PBMCs from normal donors and patients revealed that this protein was downregulated in MCF7 (p = 0.008) cells compared to normal PBMCs." (PMID 31370904, 2019).
atherosclerosis (15 papers, 2020 to 2025). A disease characterized by the build-up of fatty material and calcium deposition in the arterial wall resulting in partial or complete occlusion of the arterial lumen. "TIMER2.0 and ssGSEA showed that TYROBP expression was significantly associated with the infiltration of neutrophils, macrophages, myeloid dendritic cells and monocytes, thereby potentially influencing the progression of atherosclerosis." (PMID 41348730, 2025). "CYBB, HMOX1, IL1B, TYROBP, and CSF1R are key genes associated with ferroptosis, a form of cell death triggered by lipid metabolism abnormalities in the context of atherosclerosis." (PMID 40895546, 2025). "Analysis of tissue expression data on porcine atherosclerosis induced by high lipid factors indicates that TYROBP, ITGB2, and ITGAM are key genes influencing the progression of ankylosing spondylitis." (PMID 38382092, 2024). "The expression of the genes CYBB, FCER1G, TYROBP, IL10RA, and CSF1R is increased in both ANCA-associated vasculitis and atherosclerosis." (PMID 39702436, 2024). "Studies in animal models and humans have demonstrated that CTSS, ITGB2, and TYROBP are markers for obesity and represent possible molecular links between obesity and obesity comorbidities, such as cardiovascular diseases and atherosclerosis." (PMID 37458462, 2023). "Consistently, a recent study of vascular transcriptomics demonstrated that the trend of TYROBP mRNA was increased in high fat/cholesterol (HFC) diet-fed Tibetan minipig atherosclerosis models." (PMID 35586138, 2022). "In our study, we utilized several machine learning algorithms to determine that LAPTM5, SLC40A1, TYROBP, CTSB, and PYCARD, which are related to macrophage genes, can act as diagnostic indicators for individuals with atherosclerosis and are linked to immune infiltration in this disease." (PMID 40881888, 2025). "According to the findings of our research, the genes CYBB, FCER1G, TYROBP, IL10RA, and CSF1R could represent relevant targets for the study and development of therapeutic strategies aimed at ANCA-associated vasculitis and atherosclerosis." (PMID 39702436, 2024). "In addition, ITGB2 and TYROBP genes’ expression levels correlate with blood levels of low-density lipoprotein cholesterol (LDL-C) in the mini-pig atherosclerosis model." (PMID 37458462, 2023). "The results demonstrated significantly higher expression levels of LAPTM5, SLC40A1, TYROBP, CTSB, and PYCARD in the serum of atherosclerosis patients compared to the healthy controls." (PMID 40881888, 2025). "Our study highlights the important roles of LAPTM5, SLC40A1, TYROBP, CTSB, and PYCARD in the context of atherosclerosis." (PMID 40881888, 2025). "This study began with analyzing the GSE100927 and GSE23746 datasets to evaluate the expression levels of five key genes—TYROBP, CTSB, PYCARD, LAPTM5, and SLC15A3—in atherosclerosis-affected samples compared to normal controls." (PMID 40881888, 2025). "These six hub genes, TYROBP, ITGAM, ITGB2, CD86, PLEK, LCP2 may be important biomarkers for the progression of atherosclerosis and potential treatment targets." (PMID 38382092, 2024). "In summary, we determined that ITGAM, TYROBP, ICAM1 and CAMP may possess significant roles in mediating the chronic inflammatory process that eventually culminates in atherosclerosis and CAD." (PMID 33758323, 2021). "Interestingly, TYROBP was also identified as the high-degree gene in the PPI network of advanced plaques, indicating its core role in advanced atherosclerosis." (PMID 33519905, 2020). "RBM47, HCK, CD53, TYROBP, and HAVCR2 were identified as common hub genes, which were validated to be upregulated in advanced atherosclerotic plaques, to well distinguish CAD patients from non-CAD people and to regulate immune cell function-related mechanisms in advanced atherosclerosis." (PMID 33519905, 2020).
glioma (13 papers, 2021 to 2025). A benign or malignant brain and spinal cord tumor that arises from glial cells (astrocytes, oligodendrocytes, ependymal cells). "TYROBP expression predicted poor prognosis and high tumor immune infiltration in patients with low-grade glioma." (PMID 38767825, 2024). "Lu found that TYROBP expression was significantly higher in the low-grade glioma tissues compared to the normal tissues." (PMID 37179331, 2023). "In low-grade glioma, TYROBP has been shown to promote tumor growth and metastasis through its interaction with other proteins involved in cell signaling pathways." (PMID 37207157, 2023). "Elevated TYROBP expression predicts poor prognosis and high tumor immune infiltration in patients with low-grade glioma." (PMID 36595751, 2022). "Higher expression levels of RAB3A, SYP, CAMK2A, and GABRA1, as well as lower expression levels of TYROBP and VSIG4, in glioma patients were associated with improved OS and DFS." (PMID 36072978, 2022). "The aim of this study is to explore the clinicopathological significance, prognostic value and immune signature of TYROBP expression in low-grade glioma (LGG)." (PMID 34162355, 2021). "Elevated TYROBP expression predicted poor survival in patients with low-grade glioma." (PMID 36247009, 2022). "TYROBP expression was significantly higher in the LGG tissues compared to the normal tissues and associated with worse prognosis and poor clinic pathological parameters in glioma." (PMID 34880206, 2021). "However, little is known regarding any potential biological function of TYROBP in glioma." (PMID 34162355, 2021). "We identified six hub genes (RAB3A, TYROBP, SYP, CAMK2A, VSIG4, and GABRA1) that predicted the prognosis of glioma." (PMID 36072978, 2022). "Six hub genes related to glioma diagnosis and prognosis were identified, including RAB3A, TYROBP, SYP, CAMK2A, VSIG4, and GABRA1." (PMID 36072978, 2022). "After a series of database screening tests, we identified 11 modules during glioma progression, followed by six hub genes (RAB3A, TYROBP, SYP, CAMK2A, VSIG4, and GABRA1) that can predict the prognosis of glioma and were validated in glioma tissues by qRT-PCR." (PMID 36072978, 2022). "Therefore, it could be concluded that RAB3A, TYROBP, SYP, CAMK2A, VSIG4, and GABRA1 may play a critical role in glioma by regulating immune cells." (PMID 36072978, 2022).
Obesity (12 papers, 2019 to 2026). Accumulation of substantial excess body fat. "Through comprehensive bioinformatics analyzing and experimental verification, our study found that three hub genes CSF1R, C1QC, and TYROBP were associated with immune cells infiltration, especially macrophages in adipose tissue under obesity induced IR condition." (PMID 33564304, 2021). "This article revealed that CSF1R, C1QC, and TYROBP were potential hub genes associated with immune cells' infiltration and the function of proinflammation, especially adipose tissue macrophages, in the progression of obesity-induced diabetes or insulin-resistance." (PMID 33564304, 2021). "We applied the Attie Lab Diabetes database to verify the hub gene mRNA levels in obesity, which indicated that expression of TYROBP, TLR8, FCER1 G, HCK, NCF2, CTSS and C3AR1 was significantly up-regulated in 10-week obese mice as compared to the lean group." (PMID 32684073, 2020). "Using WGCNA, we confirmed AURKA, ITGB2, CTSS, and TYROBP as hub genes, which were identified in the coexpressed modules in PER♂, whereas AURKA was identified as a hub gene in PER♀, and these hub genes have been associated with obesity comorbidities." (PMID 37458462, 2023). "TYROBP is a hub gene in T2DM, especially in individuals with obesity-induced DM." (PMID 39916961, 2024). "The role of FCER1 G, TYROBP, CXCL16 and FCGR2A in obesity has been discussed previously." (PMID 32684073, 2020).
clear cell renal cell carcinoma (11 papers, 2019 to 2024). "Although little is known regarding TYROBP-CD44 signaling in cancer, TYROBP has been previously shown as highly expressed in clear cell renal cell carcinoma CTCs." (PMID 38106024, 2023). "In conclusion, TYROBP is highly expressed in renal clear cell carcinoma, and when this molecule is highly expressed, the survival prognosis of renal carcinoma is poor." (PMID 36595751, 2022). "It has been reported that TYROBP expression is associated with CD8 T cell infiltration in gastric cancer and clear cell renal cell carcinoma." (PMID 34336848, 2021). "have found that TYROBP is a potential prognostic biomarker for clear cell renal cell carcinoma." (PMID 35185791, 2022). "The main results of this study were that TYROBP was highly expressed in renal clear cell carcinoma." (PMID 36595751, 2022). "TYROBP is an established oncogene for clear cell renal cell carcinoma and gastric cancer." (PMID 34162355, 2021). "Furthermore, FCER1G and TYROBP have been identified as two of three hub genes in a protein-protein interaction network positively correlated with the progression of clear cell renal cell carcinoma." (PMID 31139325, 2019). "Therefore, it is speculated that TYROBP may play an essential role in developing renal clear cell carcinoma." (PMID 36595751, 2022). "We also investigated the clinical significance of TYROBP and SOX6 expression in patients with renal clear cell carcinoma." (PMID 36595751, 2022). "However, the specific molecular mechanism of TYROBP and SOX6 action in clear cell renal carcinoma remains unclear." (PMID 36595751, 2022). "TYROBP and SOX6 may be potential targets for diagnosing and treating renal clear cell carcinoma." (PMID 36595751, 2022).
osteosarcoma (11 papers, 2018 to 2024). A usually aggressive malignant bone-forming mesenchymal neoplasm, predominantly affecting adolescents and young adults. "We further investigated the association of TYROBP expression with immune cells in the osteosarcoma tumor microenvironment." (PMID 34336848, 2021). "Additionally, the study did not investigate the specific mechanisms underlying the changes in osteosarcoma cell proliferation and migration induced by the TYROBP-positive endothelial cell-conditioned medium." (PMID 37207157, 2023). "However, the underlying mechanisms of TYROBP in osteosarcoma require further in vitro and in vivo studies in the future, and these findings should be verified in a larger cohort." (PMID 36181123, 2022). "Further, GSEA was conducted to reveal the underlying mechanism of TYROBP in osteosarcoma." (PMID 36181123, 2022). "Next, we embarked on the underlying mechanisms of TYROBP in osteosarcoma." (PMID 36181123, 2022). "Then, we examined the TYROBP expression in osteosarcoma patients with various clinicopathological parameters." (PMID 36181123, 2022). "We observed a high expression of TYROBP in osteosarcoma and explored its effect on the osteosarcoma prognosis." (PMID 36181123, 2022). "Consistent with the TARGET results, the up-regulated TYROBP expression led to a favorable OS in osteosarcoma patients (HR = 0.27, P < .01)." (PMID 36181123, 2022). "Prognostic performance of TYROBP on overall survival in osteosarcoma patient subgroups by multivariate Cox regression analysis." (PMID 36181123, 2022). "More importantly, high TYROBP expression served as an independent prognostic biomarker for favorable OS in osteosarcoma patients particularly in patients of the male sex, age below 18 years, metastasis, and tumor site leg/foot groups." (PMID 36181123, 2022). "In line with these pieces of evidence, our result showed that TYROBP expression is positively correlated with CD8 T cell infiltration in the osteosarcoma tumor microenvironment." (PMID 34336848, 2021). "In conclusion, we established a new classification system of osteosarcoma based on immune signatures and identified TYROBP as a key immunoregulatory gene." (PMID 34336848, 2021). "TYROBP was significantly increased in osteosarcoma (all P < .001)." (PMID 36181123, 2022). "In conclusion, TYROBP was highly expressed in the osteosarcoma group and it might serve as a potential biomarker for improving the diagnosis and prognosis of osteosarcoma patients." (PMID 36181123, 2022). "Cox regression analysis of TYROBP expression and overall survival for patients with osteosarcoma." (PMID 36181123, 2022). "High TYROBP expression might prolong the survival of osteosarcoma patients mainly through promoting antitumor immunity." (PMID 36181123, 2022). "Furthermore, TYROBP exhibited satisfactory performance on OS of osteosarcoma patients in accordance with the Cox regression analyses and nomogram construction." (PMID 36181123, 2022). "Likewise, the forest plot illustrated the independent prognostic value of TYROBP in osteosarcoma with restricted characteristics using multivariate Cox regression results." (PMID 36181123, 2022). "Taken together, TYROBP might affect the OS of osteosarcoma patients by regulating the antitumor immune-related pathways." (PMID 36181123, 2022). "TYROBP served as an independent prognostic biomarker for OS in osteosarcoma." (PMID 36181123, 2022). "Relationship between TYROBP levels and clinicopathological parameters of osteosarcoma." (PMID 36181123, 2022). "Besides, TYROBP was highly expressed in osteosarcoma than that in osteoblast (P < .001)." (PMID 36181123, 2022). "However, the high expression of TYROBP was related to better OS in osteosarcoma patients." (PMID 36181123, 2022). "Since high TYROBP mRNA expression was closely associated with favorable OS, we next explored the clinicopathological factors that could affect its mRNA expression using GDC TARGET-osteosarcoma data." (PMID 36181123, 2022).
osteosarcoma (continued). "Besides, high TYROBP expression might prolong the OS of patients with osteosarcoma by regulating the antitumor immune-related pathways and osteoclast differentiation." (PMID 36181123, 2022). "Notably, the high immune scores group had a longer OS time than the low immune scores group, suggesting that the high TYROBP expression group might present more antitumor immune cells and hence improve the clinical outcomes of osteosarcoma patients." (PMID 36181123, 2022). "To investigate the clinical benefits of TYROBP, we performed a Kaplan–Meier plotter analysis of the GDC TARGET-osteosarcoma dataset and found that osteosarcoma patients with high TYROBP expression exhibited better OS (HR = 0.14, P < .001)." (PMID 36181123, 2022). "To elucidate the pathological function of TYROBP in osteosarcoma, we performed gene ontology annotation and KEGG pathway analyses of DEGs between high and low TYROBP expression groups." (PMID 36181123, 2022). "Using the RNA sequencing and clinical data of osteosarcoma based on therapeutically applicable research to generate effective treatments (TARGET) and gene expression omnibus (GEO), we determined the role of TYROBP in the progression of osteosarcoma by bioinformatics approaches." (PMID 36181123, 2022). "The ROC curve for TYROBP discrimination of survival status had an AUC of 0.674 and 0.625 based on TARGET-osteosarcoma and GSE21257 data, respectively, indicating that TYROBP was a reliable biomarker for distinguishing the survival status of osteosarcoma patients." (PMID 36181123, 2022). "In multivariate regression analysis, non-metastasis (HR = 0.245, P = .003) and high TYROBP expression (HR = 0.629, P = .005) were still independent factors for favorable OS in patients with osteosarcoma." (PMID 36181123, 2022). "HLA-DPA1 and TYROBP, the hub genes in PPI network were regulated by MiR-96, but their function were not researched in osteosarcoma too." (PMID 29760609, 2018).
osteoporosis (9 papers, 2013 to 2024). A condition of reduced bone mass, with decreased cortical thickness and a decrease in the number and size of the trabeculae of cancellous bone (but normal chemical composition), resulting in increased fracture incidence. "In other disease contexts, such as neuroinflammation and osteoporosis, deficiencies in TYROBP signaling lead to microglial dysfunction and impaired osteoclast differentiation." (PMID 39777260, 2024). "TYROBP is a protein involved in osteoclast differentiation, which is vital for bone absorption and has been proved to be a potential therapeutic gene for osteoporosis." (PMID 35042504, 2022). "Studies have shown that upregulated TYROBP might promote osteoporosis through osteoclasts." (PMID 35711523, 2022).